HPD (4-hydroxyphenylpyruvate dioxygenase)
Diseases named in the same sentence as HPD in open-access papers (continued):
Sharing a sentence is not in itself a finding about the gene and the disease.
tumor (17 papers, 1975 to 2025). "They investigated HpD as a diagnostic and therapeutic agent, localizing in tumor cells and inducing their fluorescence." (PMID 38675140, 2024). "This early photosensitizer, HpD, demonstrated a tendency to concentrate in tumor cells and was successful in promoting tumor shrinkage when exposed to light." (PMID 40895304, 2025). "The first generation of photosensitizers comprises HpD, historically the initial porphyrin-based photosensitizers studied on tumor cells and subsequently employed in human applications." (PMID 38675140, 2024). "The purification of hematoporphyrin led to the HpD, a combination of monomers and oligomers with tetrapyrrole structures, with remarkable fluorescent properties and affinity for the tumor cells." (PMID 36770816, 2023). "HpD was used for the first time by R. L. Lipson as an imagistic imaging agent to visualize the tumor lesion during surgery." (PMID 36770816, 2023). "Suppression of HPD expression is related to a decrease in tumor cell proliferation by altering some pathways such as pentose phosphate, RNA biosynthesis, and reactive oxygen species." (PMID 34568735, 2021). "Fluorescence lifetime imaging of mice undergoing HpD-PDT and time-gated fluorescence spectroscopy combined with post-processing revealed spatial distribution of HpD fluorescence in the tumor." (PMID 37425217, 2020). "HpD was administered via direct arterial puncture during preoperative angiogram, IV or directly into the tumor during craniotomy for tumor resection." (PMID 32039232, 2019). "Four porphyrins exhibited similar or better tumour localisation than HpD, and two (11 and 12) offer promise as lead compounds for the design of improved porphyrins for use in PDT." (PMID 1558783, 1992). "m-THPP was, on a molar basis, about 25-30 times as potent as HpD and Photofrin II in sensitising tumours." (PMID 2948536, 1986). "HpD and Photofrin II induced modest tumour photosensitisation at the cost of substantial skin and brain sensitisation." (PMID 2948536, 1986). "The protein levels of TPI and ENO1 were significantly decreased in the HPD knockdown tumor tissues." (PMID 40491422, 2025). "Thus, targeting the RBD domain of HPD disrupts its RNA binding ability, leading to blocking glycolysis flux, tumor growth, and enhancing drug response." (PMID 40491422, 2025). "A mercury lamp to activate HpD and a quartz rod were used to attempt to destroy the tumor." (PMID 39125828, 2024). "All these findings indicate the potential role of HPD in tumor formation and progression." (PMID 31285420, 2019). "The tumour necrosis was at least as good as that of HpD, and this therapeutic response may be attributed to the targeting of specific 'photopotent' subcellular sites." (PMID 8080721, 1994). "Finally, we conducted a gene network analysis of the DEFA gene and found that there were tumor-suppressor-related genes associated with DEFA, including FGF21 and ITLN1, as well as tumor-promoting genes associated with DEFA, including GNB3, CRB2, DIO3, HPD, and Dll3." (PMID 41009818, 2025). "HpD or light alone caused no damage to tumours or normal tissues." (PMID 1164470, 1975). "To address the role of HPD in promoting tumor growth mediated by PPP flux, we first compared the expression and activities of enzymes involved in PPP between systems with different HPD expression." (PMID 31285420, 2019). "Suppressed HPD expression was sufficient to decrease oxidative pentose phosphate pathway (PPP) flux, leading to reduced RNA biosynthesis and enhanced reactive oxygen species (ROS) level, attenuated cancer cell proliferation, and tumor growth." (PMID 31285420, 2019). "The mRNAs levels of HPD, TPI, and ENO1 were not significantly different between tumor tissues and normal ovarian tissues." (PMID 40491422, 2025).
cancer (12 papers, 2013 to 2025). A tumor composed of atypical neoplastic, often pleomorphic cells that invade other tissues. "Kyoto Encyclopedia of Genes and Genomes (KEGG) pathway analysis and Gene Ontology (GO) analysis on the 5053 RNAs enriched by HPD, which are crucial for cancer progression, including the cell cycle and glycolysis pathways." (PMID 40491422, 2025). "4‐hydroxyphenylpyruvate dioxygenase (HPD) is an important metabolic enzyme in the tyrosine metabolic pathway and displays aberrant expression and function in cancer." (PMID 40491422, 2025). "HPD is a novel RNA‐binding protein, and this moonlighting function highlights the knowledge of HPD in regulating cancer development and drug response beyond only as a metabolic enzyme." (PMID 40491422, 2025). "In order to analyze the cytotoxicity induced by Au-HpD, cancer cells and normal cells were co-cultured in the presence of Au-HpD; then, they were subjected to 870 nm laser irradiation." (PMID 35209026, 2022). "The analysis showed that Au-HpD absorption in RGK1 cancer cells was significantly higher than in RGM1 normal cells." (PMID 35209026, 2022). "To obtain effective cancer-specific accumulation of AuNPs, we focused on porphyrin and synthesized a porphyrin-attached Au compound: Au-HpD." (PMID 35209026, 2022). "Since then, many studies have reported attempts of PDT with HpD (or its more active commercial form; photofrin II) in many types of cancers." (PMID 32024010, 2020). "In our study, MnSOD overexpression in cancer cells decreased HpD accumulation, thereby attenuating the effects of PDT6." (PMID 30733583, 2019). "In this study, we demonstrated for the first time that a hyperthermia pretreatment increased intracellular HpD accumulation, thereby enhancing cancer-specific PDT cytotoxicity by the upregulation of ROS production." (PMID 30733583, 2019). "In this respect, translational control of glycolysis enzymes mRNA by tyrosine catabolism enzyme HPD, which may be a fast way of controlling cancer progression by reprogram aerobic glycolysis." (PMID 40491422, 2025). "Thus, blocking the RBD domain of HPD destroys its RNA‐binding function, thereby inhibiting global mRNA translation, leading to the inhibition of cancer development." (PMID 40491422, 2025). "Taking into consideration that cancer cells incorporate higher levels of porphyrins than normal cells, we analyzed whether Au-HpD has any preferential accumulation in cancer cells." (PMID 35209026, 2022). "In this study, we investigated whether Au-HpD possesses cancer-specific accumulation and cytotoxicity." (PMID 35209026, 2022). "According to the porphyrin attachment, Au-HpD obtained the cancer-specific accumulation." (PMID 35209026, 2022). "Au-HpD accumulation in cancer cells was higher than in normal cells." (PMID 35209026, 2022). "The results reported here may not only help to understand the function and oncogenic potential of HPD, but also have implications in developing new strategies for cancer prevention and treatment." (PMID 31285420, 2019). "Moreover, HpD accumulation was also inhibited by NAC in cancer cells." (PMID 30733583, 2019). "Results indicated high expression of IL4I1, TDO2, NIT2, and IDO1, while IDO2, ADI1, DDC, HPD, BHMT2 exhibited low expression in most cancers." (PMID 38691253, 2024). "In 1966, treatment of cancers using PS, now known as PDT, was first applied to breast cancer, using HpD." (PMID 32024010, 2020). "Second, pan-cancer co-expression analysis for miRNA-target interaction in HCC using starBase showed that miR-539 level negatively correlated with TAT, HPD, GSTZ1 and FAH expression (r = -0.221, r = -0.193, r = -0.123, r = -0.166)." (PMID 32542016, 2020). "From these results, we concluded that the hyperthermia treatment increased mitROS production, which involved HpD accumulation and enhanced PDT effects in cancer cells." (PMID 30733583, 2019).
genetic diseases (2 papers, 2019 to 2025). "4-Hydroxyphenylpyruvate dioxygenase inhibitors (HPPDi) are mainly used as herbicides and for therapeutic use in genetic diseases of tyrosine catabolism." (PMID 41028238, 2025).
inherited metabolic disorders (1 paper, 2021). "4-hydroxyphenylpyruvate dioxygenase (HPD) is a key enzyme in the catabolism of tyrosine and therefore of great importance as a drug target to treat tyrosine-related inherited metabolic disorders (TIMD)." (PMID 33365261, 2021).
HPD also shares sentences with these, for which no sentence is quoted: infection (5 papers); breast carcinoma (4); liver failure (2); metabolic disorders (2); Acidosis (1); acute liver failure (1); adrenoleukodystrophy (1); cardiovascular diseases (1); COVID-19 (1); extramammary Paget disease (1); Hepatitis (1); hepatoblastoma (1); liver disease (1); lung adenocarcinoma (1); neurological disorders (1); Pallister-Killian Syndrome (1); pancreatic ductal adenocarcinoma (1); persistent Mullerian duct syndrome (1); renal tubular dysfunction (1); tauopathies (1); thyroid cancer (1); tyrosinemia type II (1); viral infections (1); vitiligo (1).